CCL2 (C-C motif chemokine ligand 2)
Diseases named in the same sentence as CCL2 in open-access papers (continued):
Sharing a sentence is not in itself a finding about the gene and the disease.
tumor (continued). "CCL2 is a crucial chemokine that promotes tumorigenesis and an immune‐compromised tumor microenvironment." (PMID 40285526, 2025). "They preferentially home to tumours through chemokines such as CCL2 and CCL20, making them advantageous for solid tumour targeting." (PMID 41292193, 2025). "HCC patients’ monocytes are recruited to the tumor mass by C-C motif chemokine ligand 2 (CCL2), and different subsets of monocytes appear during the cancer progression." (PMID 40136652, 2025). "CCL2 can be continuously produced by tumor cells, stromal cells, and host–tumor interactions through constitutive secretion, microenvironmental stimulation response, and interaction network." (PMID 41341593, 2025). "The peripheral blood of cancer patients contains a lot of transitory monocytes migrating to the tumor site or the pre-metastatic niche following chemokine stimuli like CCL2, CCL5, CCL7, and CCL12." (PMID 40427136, 2025). "CCL2 is one of the most prevalent cytokines expressed in the tumor microenvironment and is considered as one of the major chemoattractants of monocytes/macrophages at sites of inflammation." (PMID 40112045, 2025). "In prostate cancer, tumor-derived CXCL8 induced CCL2 gene expression in WPMY-1 fibroblasts and THP-1 cells." (PMID 41341593, 2025). "EZH2 reduction resulted in DNA demethylation and subsequent elevation of miR-124-3p levels, inhibiting its target CCL2 production in tumor cells and inhibiting M2-type TAM polarization." (PMID 39858015, 2025). "For example, CCL2 recruits monocytes to tumors, where they can differentiate into TAMs that support tumor growth and metastasis by releasing cytokines and growth factors." (PMID 41326332, 2025). "In B‐cell lymphomas, decreased H3K27 acetylation suppresses FBXW7 expression, activates the NOTCH signaling pathway and downstream CCL2/CSF1, and promotes tumor cell proliferation and M2 polarization of tumor‐associated macrophages (TAMs)." (PMID 40761481, 2025). "CCL2 also blocks CD8+ T cell infiltration into tumor cells by binding to its CCR2 receptor on T cells." (PMID 41463161, 2025). "To home M2 macrophages, which are the predominant myeloid population in the tumor periphery, toward the cryogel, we deliver chemokine (C-C motif) ligand 2 (CCL2)." (PMID 40883548, 2025). "In BCBM, CCL2 can be spontaneously generated by BC cells through NF‐κB, TNFα, and other pathways and can also be generated by tumor cells stimulated by microenvironment, or by stromal cells." (PMID 39712454, 2025). "Elevated tumor glycolysis attracts monocytes/macrophages via the ENSA-K63la/SRC-pS12/STAT3-pY705/CCL2 axis." (PMID 39883522, 2025). "For instance, CD62L/CD62L ligands, CCR2/CCL2, VEGF receptor R1/VEGF-A, and CX3CR1/CX3CL1 receptor-ligand pairs have been most prominently associated with the recruitment of monocytes to the tumor microenvironment." (PMID 41440002, 2025). "Gemcitabine drug-resistant Gal-3-high tumor cells can increase the expression of CCL2 and BSG in TAFs through the Ca2+–calcineurin–NFAT pathway, thereby leading to mitochondrial oxidative phosphorylation suspension via CCL2–CCR2 cell signaling." (PMID 40600063, 2025). "CCL2 blockade significantly slowed primary tumour growth and inhibited lung metastases in NSCLC models by altering TAMs to a more anti-tumour phenotype and activating CTLs." (PMID 40385641, 2025). "Studies indicate that the epigenetic regulatory factor bromodomain-containing protein 4 enhances the expression of the transcription factor cellular Jun proto-oncogene, which in turn promotes tumor cells to secrete CCL2, facilitating macrophage recruitment." (PMID 40861469, 2025). "Analysis of tumor-infiltrated lymphocytes revealed that KD of Hk2 or inhibiting CCL2 signaling in KPC tumors reduced monocyte/macrophage infiltration but enhanced T cell infiltration and function." (PMID 39883522, 2025).
tumor (continued). "Tumor angiogenesis plays a crucial role in tumor growth, maintenance and metastasis, and CCL2/CCR2 axis plays a key role in the angiogenesis of OSCC." (PMID 41445742, 2025). "CAAs are better equipped to support tumor invasion and metastasis by releasing CCL2, CCL5, CXCL8, IL-6, leptin, adiponectin, and VEGF." (PMID 40076892, 2025). "LISA and RT-PCR assays demonstrated that gefitinib dose-dependently reduced CCL2 secretion in Cal-27 tumor spheroids, while FMD significantly reversed gefitinib-induced CCL2 suppression at both protein and mRNA levels." (PMID 40808689, 2025). "These TAMs, once recruited by the CCL2 secreted by resistant cancer cells, were polarized into an M2 phenotype, which is known to promote tumor progression and further enhance resistance to paclitaxel." (PMID 40330466, 2025). "Tumor cells secrete chemokines like CCL2, CCL5, and CSF-1 that recruit monocytes from the bloodstream into the TME, where they differentiate into TAMs." (PMID 39930476, 2025). "Synergistically, the CCL2/CCR2 axis reinforces this immunosuppressive milieu by attracting macrophages with tumor‐promoting phenotypes." (PMID 40145607, 2025). "Increased CD163+ and CD68+ cell count (representing M2 type macrophages and all tumour associated macrophages respectively) and increased MCSF and CCL2 expression, in both LARC biopsy and resection specimens, were associated with inferior overall survival." (PMID 41487587, 2025). "To assess the role of tumor-derived chemokines on metastasis, we prepared Ccl2 knock-down (Ccl2KD) tumor cells using shRNA lentivirus transduction." (PMID 39566333, 2025). "The migration of monocytes derived from BL6, Ccr1-/- and Ccr2-/- mice was dependent on tumor cell-derived Ccl2 in the CM, since migration towards CM from Ccl2KD tumor cells was reduced." (PMID 39566333, 2025). "Through its interaction with the NF-κB pathway, CCL2 facilitates the recruitment of monocytes and macrophages to the tumor site, promoting tumor growth, invasion, and metastasis." (PMID 40940890, 2025). "Anti-CD40 antibodies exert tumor-suppressive effects by engaging tumor-infiltrating macrophages and increasing levels of CCL2 and IFNγ, thereby enhancing tumor cell elimination." (PMID 40343509, 2025). "The encapsulation of oAd into CCL2-coated liposomes that were preferentially taken up by CCR2-expressing monocytes was able to significantly reduce tumor size and pulmonary metastasis burden in prostate cancer-bearing mice." (PMID 40723180, 2025). "The overexpression of CCL2 chemokine in tumours like glioblastoma, bladder, prostate, breast, ovarian, gastric, melanoma and renal cell carcinoma facilitates the recruitment of CCR2+ LY6C+ M-MDSCs, causing a higher tumour load and reduced overall survival." (PMID 40852716, 2025). "It upregulates CCL2 in tumor-adipocyte co-culture, which in turn recruits and polarizes M2 TAM to promote BC growth." (PMID 41341593, 2025). "ADSCs are recruited to the TME via tumor-secreted chemotactic signals, such as CCL2 and CXCL12, where they undergo functional reprogramming to adopt pro-tumorigenic roles." (PMID 40510466, 2025). "Tumor fibrosis, characterized by excessive extracellular matrix deposition, is driven by chemokines such as CCL2 and CCL5, which attract fibroblasts to the TME." (PMID 40134607, 2025). "Mechanistically, the proteasome activator PA28γ (REGγ) promotes tumor cell secretion of IL-6 and CCL2 by activating the p-NF-κB pathway." (PMID 41445742, 2025). "The higher level of pro-tumor CCL2 was also observed in treatment group, which need further investigation in future." (PMID 41462289, 2025). "Recent studies have shown that HER2 itself regulates the recruitment of tumour-infiltrating immune cells by inducing the expression of chemokine ligand 2 (CCL2) and PD-1 ligands, thereby enhancing the efficacy of immunotherapy." (PMID 40291906, 2025).
tumor (continued). "Monocytes and macrophages are actively recruited to the tumor site and differentiate into TAMs upon induction by factors such as IL-6, CCL2, and GM-CSF present in the TME." (PMID 40083697, 2025). "Both Gal-3 and CCL2 enhanced the formation of tumor spheres, and this process was inhibited by the CCR2 inhibitor." (PMID 40600063, 2025). "The results showed that the transcriptomic expression level of CCL2 is significantly positively correlated with the sensitivity to the TOP30 anti-tumor drugs, while the other five genes exhibit varying degrees of negative correlation with most drugs." (PMID 40718780, 2025). "In the tumor’s infiltrative zones, PTEN-deficient GBM cells secrete increased levels of C-C Motif Chemokine Ligand 2 (CCL2), facilitating the recruitment of myeloid cells, thereby promoting tumor growth and suppressing immune activity." (PMID 39859381, 2025). "Intraperitoneal administration of a CCL2-neutralizing antibody significantly suppressed EV accumulation in lung tissues and lung metastasis in orthotopic OS tumor model mice." (PMID 40343498, 2025). "Neutralizing antibodies targeting VEGF or CCL2 have shown promise in reducing tumor angiogenesis and progression." (PMID 40647432, 2025). "As observed with chemotherapy, radiotherapy similarly alters the phenotype of CCL2/CCR2-recruited monocytes towards tumor-supporting Mo-MDSCs, which promotes radioresistance." (PMID 41440002, 2025). "Our integrated findings establish a feedforward resistance loop: Gefitinib treatment paradoxically enhances tumor cell CCL2 secretion, driving TAMs infiltration that subsequently secretes protective factors to diminish drug efficacy." (PMID 40808689, 2025). "High IL-6 and CCL2 levels frequently correlate with worse clinical outcomes, reflecting a synergy among TANs, tumor cells, and other suppressive immune populations that ultimately restrict T-cell-mediated clearance." (PMID 40281554, 2025). "In the context of cervical cancer, SCs secrete the cytokine CCL2 to promote PNI through the activation of EMT in tumour cells." (PMID 40037534, 2025). "For example, tumor-derived conditioned medium containing high levels of CCL2, CXCL1, and CXCL5 inhibits DC maturation in vitro." (PMID 41445742, 2025). "CCL2 is a key chemokine involved in recruiting TAMs and other immunosuppressive cells, contributing to tumor growth, angiogenesis, and metastasis." (PMID 40806751, 2025). "Among the various subtypes of fibroblasts/myofibroblasts, OMD+ fibroblasts were specifically present in LNM PDAC and were found to create a tumor-permissive microenvironment by recruiting CCL2+ macrophages." (PMID 40092486, 2025). "In anaplastic thyroid carcinoma (ATC) in humans, PPARγ agonists can inhibit the secretion of CCL2 in some tumor cells and simultaneously suppress the activation of NF-κB and ERK1/2 signaling pathways." (PMID 41341593, 2025). "Tumor cells secrete a wide array of cytokines and chemokines such as CCL2, CSF-1 (M-CSF), IL-6, IL-10, and TGF-β that directly polarize macrophages." (PMID 41425545, 2025). "Abnormal tumor vessels further exacerbate hypoxia, which in turn increases the secretion of chemotactic cytokines - including CCL2, CCL22, CCL28, CXCL8, and CXCL12 - that recruit immunosuppressive MDSCs, M2-like TAMs, and Tregs into the tumor." (PMID 41019982, 2025). "In the PMN, monocytes act together with neutrophils, also recruited by tumor-derived CCL2 stimuli, and facilitate tumor cell colonization." (PMID 40427136, 2025). "The increased IL‐6, in turn, elevates EIF4A3 and CCL2 levels within tumor cells, which upregulate circSERPINE2 biogenesis in tumor cells and promote the recruitment of TAMs in a positive feedback mechanism." (PMID 39901896, 2025). "Previous studies have indicated that tumor cells can produce CCL2, which induces the infiltration and migration of various immune cells and plays a crucial role in the immune response." (PMID 38216673, 2024).
tumor (continued). "The mentioned effects are probably mediated through increased CCL2 production by tumor cells in response to anti-CCL2 therapy, which dramatically increases the availability of CCL2 after treatment cessation." (PMID 39003350, 2024). "Monocytes are recruited to tumor sites via the CCL2/CCR2 axis, inhibiting CD8+ T cell infiltration and recruiting Tregs." (PMID 39253716, 2024). "Carlumab, a monoclonal antibody targeting CCL2, has shown efficacy in reducing prostate-specific antigen levels and inhibiting tumor progression in a phase II clinical trial." (PMID 39717759, 2024). "At the same time, tumor cells secrete chemokines such as CCL2 in order to attract inflammatory monocytes, which subsequently facilitate the metastatic establishment of the tumor by secreting VEGF." (PMID 38243240, 2024). "The expression of CCL2 in BCa is found to play a significant role in modulating the TME through the recruitment of pro-tumor immune cells including TAMs and MDSCs." (PMID 39409924, 2024). "High CCL2 expression on ESCC cells induces monocytes and tumor‐associated macrophages, advancing immune evasion." (PMID 39415846, 2024). "Targeting the CCL2/CCR2 axis has previously been shown to inhibit HCC tumour growth and metastasis by reducing monocyte and TAM infiltration and increasing CD8+ T-cell cytotoxic activity." (PMID 39684877, 2024). "Transwell results suggest that CCL2 in the BCa TME has a chemotactic effect, and Mast-CCL2 can recruit peripheral blood monocyte-derived macrophages to the tumor microenvironment by secreting the chemokine CCL2." (PMID 39308672, 2024). "Analysis of tumor-associated RNA revealed high JAK2, PD-L1, CCL2, and CXCL10 expression in ALKBH5-overexpressing mice compared to wild-type mice." (PMID 38872221, 2024). "It was observed that the use of the CCL2-neutralizing antibody significantly reversed the CM-BMA-PA-induced deteriorated biological behavior and elevated the expressions of tumor-associated genes in PC-3 cells." (PMID 38221626, 2024). "These cells have been described to be pro-inflammatory in function and are recruited to tumor tissue in response to CCL2/CCR2 signaling." (PMID 38444857, 2024). "Overall, these data demonstrate that early tumor suppression is primarily due to synergy therapy-induced apoptosis, while late distal tumor regression is attributed to CCL2-mediated T cell migration." (PMID 39578426, 2024). "For instance, they recruit TAMs to perineural invasion sites via C‒C motif chemokine ligand 2 (CCL2), which exacerbates nerve damage and tumor cell invasion." (PMID 39492832, 2024). "In order to better simulate the effect and mechanism of the Ly6Chigh monocytes and neutrophils infiltration induced by cisplatin in vivo, we established LL2 tumour‐bearing model in WT mice, CCL2−/− mice and LTB4R−/− mice, and treated them with cisplatin." (PMID 37905494, 2024). "In turn, increased CCL2 on tumor cells recruits microglia to stimulate proliferation and inhibit apoptosis of metastatic brain cancer cells." (PMID 37307835, 2024). "This elegant study revealed, for the first time, a string of CCL2-triggered metastatic processes, CCL2–monocyte–VEGFα–tumor extravasation–tumor metastasis." (PMID 38786066, 2024). "Neutrophils play a role in promoting the recruitment of other myeloid cells into the tumor bed through the release of chemokines such as CCL2, CCL3, and CCL4, which attract monocytes and dendritic cells." (PMID 38426089, 2024). "While the mice model of HNSCC treated with radiotherapy, there showed an increase in the production of the chemotactic factor CCL2 in tumor cells, leading to the accumulation of CCR2-dependent TNF-α-producing monocytes/macrophages and CCR2+ Tregs." (PMID 38650924, 2024). "In inflammatory breast cancer, knockdown of CCL2 markedly reduces macrophage density, tumor growth, skin erythema, and metastasis." (PMID 39199574, 2024).
tumor (continued). "In our study, we found that IFI35 promoted the secretion of tumor-derived CCL2, which led to the infiltration of MDSCs to promote TNBC immune escape." (PMID 38216673, 2024). "Circ‐0009092 regulates STAT3 modification and reduces CCL2 expression by targeting the miR‐665/NLK signaling axis, which inhibits tumor‐associated macrophage aggregation and slows down the EMT progression of tumor." (PMID 39584047, 2024). "One of the cytokines identified was CCL2 (C-C motif chemokine ligand 2), which was upregulated in cisplatin-resistant tumours (logFC = 1.23, p = 0.011)." (PMID 38809883, 2024). "Another study reported that CCL2 induced by hypoxic tumor cells can inhibit the maturation of NK cells in the pre‐metastatic niche and reduce their ability to eliminate incoming circulating tumor cells, thereby accelerating the homing of tumor cells to CCR2." (PMID 38468260, 2024). "IL-6, in turn, in a positive feedback mechanism, boosts intra-tumoral EIF4A3 and CCL2 levels, further enhancing tumor cSERPINE2 biosynthesis and promoting TAM recruitment." (PMID 39068459, 2024). "Tumor-secreted TGF-β facilitates the recruitment of N2 neutrophils which later creates an immunosuppressive microenvironment by producing CCL2 and CCL17 in a paracrine manner." (PMID 38520006, 2024). "The recruitment of EPCs by CAF-derived CCL2 has been observed in breast cancer models, where it promotes tumor angiogenesis and growth." (PMID 39519109, 2024). "For example, tumor-derived microparticles (T-MPs) can induce macrophages to release C-C motif ligand 2 (CCL2), a key chemokine." (PMID 39737395, 2024). "Both RT-qPCR and ELISA confirmed that Ifi35ko 4T1 and EMT6 tumor cells overexpressing Ccl2 had increased mRNA expression and secretion of CCL2." (PMID 38216673, 2024). "CCL2, also known as MCP‐1, is a potent recruiter of MDSCs and stimulates their migration to tumour sites." (PMID 37905494, 2024). "We show that unlike N-NCMs, I-NCMs migrated into both vascular and extravascular tumor microenvironments via the CCR2/CCL2 axis, where they released CCL6 to recruit NK cells that promote tumor lysis, independent of T and B lymphocytes." (PMID 39545417, 2024). "A recent study advocated that targeting tumor cell-derived CCL2 seems to be a feasible strategy to overcome bevacizumab resistance in Etv5+ CRC." (PMID 38419056, 2024). "CCL2 siRNA-mediated knockdown in MDA-MB-231 breast xenografts has been shown to inhibit primary tumor growth and metastasis." (PMID 38973385, 2024). "Tumor-associated neutrophils (TANs) produced chemokines such as CCL2 and CCL17, which later recruited TAMs and Tregs and promoted tumor growth in HCC." (PMID 38362156, 2024). "Quantitative analysis showed that the proportion of CCL2 expression increased from 4.72 ± 1.02% in the CAR-T group to 11.48 ± 1.91% in the synergy group in the local tumor." (PMID 39578426, 2024). "CCL2 depletion in vivo led to a decrease of phosphorylated STAT3 (pSTAT3) levels in tumor-infiltrating MDSCs." (PMID 38448555, 2024). "In mouse tumor models, CRISPR screening was performed, revealing a significant loss of tumor suppressor genes (TSGs) and a notable enrichment of CCL2/MCP1 genes, along with an accumulation of MDSCs." (PMID 39456702, 2024). "Previous studies have demonstrated that CCL2 can recruit MDSCs infiltration to form an immunosuppressive microenvironment, which helps tumor cells evade the attack of immune cells and supports tumor cell proliferation." (PMID 38216673, 2024). "CCL2 is the most significantly differentially expressed gene between FL-MSCs and HD-MSCs and promotes the migration of monocytes to tumor sites." (PMID 38779660, 2024). "In neuroblastoma, chemotherapy leads to the selective expansion of CCL2-expressing mesenchymal-like tumor cells and macrophage infiltration in patients, which promotes relapse and chemo-resistance." (PMID 39555068, 2024). "The AS‐99 also reduced the H3K4me3 modification and expression of CSF1 and CCL2 in both tumor cells and HSCs." (PMID 39377228, 2024).